LINC00958 (long independently transcribed non-coding RNA 958)
Synonyms: BLACAT2
Gene: Long non-coding RNA gene on chromosome 11 (12,961,541 to 12,989,597, reverse strand). Ensembl gene ENSG00000251381.
Diseases named in the same sentence as LINC00958 in open-access papers:
LINC00958 is named in the same sentence as 32 diseases in open-access papers, as found by Europe PMC text mining. Sharing a sentence is not in itself a finding about the gene and the disease. The quoted sentences say what the papers report.
bladder cancer (19 papers, 2018 to 2024). "Moreover, LINC00958 has been implicated in various cancer types, including bladder cancer, breast cancer and hepatocellular carcinoma." (PMID 38218927, 2024). "Another study screened the online database GEPIA and found that linc00958 was upregulated in all urinary tumours, including bladder cancer." (PMID 36831352, 2023). "Linc00958 is located on 11p15.3 and was found to be substantially expressed in bladder cancer tissues compared to normal bladder epithelial tissues." (PMID 36831352, 2023). "LINC00958 has a regulatory role in bladder cancer progression, as its knockdown decreases cell viability, migration, and invasion." (PMID 32517366, 2020). "Increased expression of LINC00473 in HNSCC; LINC00114, MINCR and PVT1 in NPC; Linc-RA1 in glioma; LINC00473and CYTOR in NSCLC; NEAT1 and LINC00958 in cervical cancer; H19 in cardiac cancer; LINC02582 in breast cancer; and TUG1 in bladder cancer were associated with radioresistance." (PMID 36323697, 2022). "LINC00958 was originally recognized as a cancer-promoting gene in bladder cancer." (PMID 35676262, 2022). "To investigate whether LINC00958 plays a key role in bladder cancer, we performed a series of experiments in cells transfected with Si-lnc." (PMID 34702201, 2021). "To expand the downstream network of LINC00958, we first analyzed the GSE40355 and GSE37815 data series to identify differentially expressed miRNAs (DE-miRs) and differentially expressed mRNAs (DE-mR) in bladder cancer samples." (PMID 34702201, 2021).
hepatocellular carcinoma (12 papers, 2020 to 2024). A malignant tumor that arises from hepatocytes. "The expression of LINC00958 in hepatocellular carcinoma was also influenced by METTL3 in an N6 methylation-dependent manner." (PMID 35223488, 2022). "For example, METTL3-mediated m6A methylation modification, resulting in LINC00958 upregulation by stabilizing its RNA transcript and the high level of LINC00958, led to the poor overall survival of hepatocellular carcinoma patients." (PMID 35562992, 2022). "Similarly, METTL3-mediated m6A methylation modification can up-regulate LINC00958, resulting in low overall survival in patients with hepatocellular carcinoma." (PMID 36429081, 2022). "Thus, LINC00958 can be considered to be a therapeutic target for the systemic treatment of hepatocellular carcinoma using siRNA." (PMID 34003875, 2021). "Similarly, LINC00958 was stabilized by METTL3 (writer), and upregulated LINC00958 was involved in the malignancy of hepatocellular carcinoma progression by sponging miR-3619-5p." (PMID 34238292, 2021). "In hepatocellular carcinoma, METTL3 mediates the m6A modification of LINC00958, leading to the upregulation of LINC00958 through stabilizing its RNA transcript, then upregulates hepatoma-derived growth factor (HDGF) expression." (PMID 35501316, 2022). "In hepatocellular carcinoma (HCC), METTL3-mediated m6A modification enhances the stability of LINC00958 transcript, which can upregulate hepatoma-derived growth factor (HDGF) expression by sponging miR-3619-5p to promote tumor growth." (PMID 33292652, 2020). "For instance, METTL3-mediated m6A modification led to LINC00958 upregulation through stabilizing its RNA transcript, and LINC00968 sponged miR-3619-5p to upregulate HDGF expression thereby facilitating the lipogenesis and progression of hepatocellular carcinoma (HCC)." (PMID 32982586, 2020). "Also, in hepatocellular carcinoma (HCC), METTL3 stabilizes LINC00958, Snail, and CTNNB1, thereby contributing to cellular processes such as lipogenesis, proliferation, metastasis, and tumor growth." (PMID 38966069, 2024).
gastric cancer (9 papers, 2021 to 2026). A primary or metastatic malignant neoplasm involving the stomach. "LINC00958 has been extensively studied in some cancers such as head and neck cancers, gastric cancer, lung cancer, and cervical cancer." (PMID 34702201, 2021). "In gastric cancer, KIAA1429 increases the m6A modification of Linc00958, which can significantly up-regulate the expression of Linc00958." (PMID 35022030, 2022). "Not only that, in gastric cancer (GC), KIAA1429 overexpression promotes LINC00958 RNA residue levels and KIAA1429 regulates LINC00958 enrichment, which accelerates aerobic glycolysis in GC cells." (PMID 38125749, 2023).
cervical cancer (7 papers, 2021 to 2022). A primary or metastatic malignant neoplasm involving the cervix. "Linc00958 was revealed earlier in cervical cancer as an oncogenic gene, promoting the cell proliferation and invasion, and its downregulation sensitized the cells to radiation through miR-5095/RRM2." (PMID 36056431, 2022). "For example, LINC00958 is significantly overexpressed in cervical cancer tissues and cells and promotes cervical cancer cell metastasis and proliferation by sponging miR-625-5p/LRRC8E16." (PMID 33531456, 2021). "linc00958 was reported to be an oncogene in cervical cancer." (PMID 36056431, 2022). "The expression of LINC00958 in cervical cancer tissue was higher than that in normal tissue, and the high expression of LINC00958 was negatively correlated with the overall survival of cervical cancer." (PMID 35692795, 2022). "Moreover, linc00958 expression was correlated with a short survival in cervical cancer patients." (PMID 36438563, 2022). "Mechanistically, linc00958 regulated miR-185-5p and RSF-1 and modulated cisplatin resistance in cervical cancer cells via targeting AKT1/GSK3β/VEGFA pathway." (PMID 36438563, 2022). "Further, linc00958/RSF-1 downregulation or miR-185-5p upregulation could alleviate the cisplatin resistance and tube formation in cervical cancer cells via AKT1/GSK3β/VEGFA pathway." (PMID 36056431, 2022).
colorectal cancer (6 papers, 2021 to 2022). A primary or metastatic malignant neoplasm that affects the colon or rectum. "Our results provide insight into the progression and radiosensitivity of colorectal cancer and suggest that LINC00958 may serve as a promising diagnostic, prognostic and therapeutic marker for colorectal cancer." (PMID 34496838, 2021). "Kaplan–Meier survival analysis indicated that colorectal cancer patients with higher LINC00958 expression had worse overall survival and disease-free survival than those with lower LINC00958 expression." (PMID 34496838, 2021). "We found that LINC00958 is upregulated in colorectal cancer tissues and positively correlated with clinicopathological features and poor prognosis." (PMID 34496838, 2021). "Further rescue experiments identified that miR-422a reversed the roles of LINC00958 in colorectal cancer progression." (PMID 34496838, 2021). "We found that LINC00958 expression was upregulated in colorectal cancer tissues compared with matched normal tissues (82.54%, 52/63)." (PMID 34496838, 2021). "Collectively, our results demonstrate that LINC00958 promotes colorectal cancer cell proliferation in vivo." (PMID 34496838, 2021). "Since lncRNAs exert biological functions mainly by acting as miRNA sponges, we explored whether LINC00958 promotes colorectal cancer progression by sponging miRNAs." (PMID 34496838, 2021). "The results showed that the expression of S100A2, DKK3 and SCHIP1, which play a role in colorectal cancer, HNSC, and gallbladder cancer, was significantly correlated with the expression of LINC00958." (PMID 36437914, 2022). "The expression of LINC00958, miR-3064-5p, and LEM domain containing 1 (LEMD1) in colorectal cancer tissues and cell lines was analyzed using reverse transcription quantitative polymerase chain reaction (RT-qPCR)." (PMID 34672237, 2021).
breast carcinoma (5 papers, 2019 to 2024). "For instance, LINC00958 regulated by m6a modification can promote breast cancer tumorigenesis through miR-378a-3p and YY1 axis." (PMID 34026852, 2021). "Reduced expression of BLACAT1 in HNSCC; MALAT1, NEAT1 and PVT1 in NPC; FAM201A, PVT1 and LINC00857 in NSCLC; LINC00473, CCAT2and Rpph1 in EC; HOTAIR and LINC00958 in CRC; AFAP1-AS1 and LINC00511 in breast cancer were correlated with radiosensitivity." (PMID 36323697, 2022).
pancreatic cancer (5 papers, 2020 to 2021). "For example, LINC00958 deletion prevented tumor initiation by sponging the miRNA-330-5p to regulate PAX8 expression in pancreatic cancer." (PMID 32127947, 2020).
head and neck squamous cell carcinoma (4 papers, 2020 to 2022). A squamous cell carcinoma that arises from any of the following anatomic sites: lip and oral cavity, nasal cavity, paranasal sinuses, pharynx, larynx, and salivary glands. "LINC00958 has been found to be associated with cell adhesion, extracellular matrix organization, and human papillomavirus infection in head and neck squamous cell carcinoma." (PMID 36437914, 2022). "Previously, linc00958 downregulation was confirmed to decrease chemo- and radio-resistance in head and neck squamous cell carcinoma in vitro." (PMID 36056431, 2022).
nasopharyngeal carcinoma (3 papers, 2021 to 2023). A carcinoma arising from the nasopharyngeal epithelium. "LINC00958 acts as a ceRNA to regulate the miR-625/NUAK1 axis, and affects the invasion and metastasis of nasopharyngeal carcinoma cells." (PMID 37576402, 2023). "LINC00958 plays a role in multiple cancers by upregulating the microRNA-625/NUAK pathway and contributes to nasopharyngeal carcinomas." (PMID 34660307, 2021).
endometrial cancer (2 papers, 2019). Primary or metastatic malignant neoplasm involving the endometrium (mucous membrane that lines the endometrial cavity). "Chen and colleagues showed that LINC00958 was overexpressed in endometrial cancer, and LINC01480 was shown to be required to express the micropeptide." (PMID 31804973, 2019). "Our work suggests that LINC00958 may regulate DOLPP1 by “sponging” miR‐761 in endometrial cancer." (PMID 31338870, 2019).
head and neck carcinoma (2 papers, 2021 to 2022). A carcinoma that arises from the head and neck region. "In head and neck carcinoma, linc00958 interacts with MYC and mediates cellular resistance to cisplatin and radiation, suggesting that linc00958 might regulate cisplatin resistance in CC." (PMID 36056431, 2022).
lung carcinoma (2 papers, 2021 to 2022). "Consistent with the previously reported function of LINC00958 as an oncogene in other cancer types, this study demonstrated that LINC00958 promotes lung cancer growth and metastasis and inhibits cancer cell apoptosis." (PMID 35223488, 2022).
lymph node metastasis (2 papers, 2021 to 2022). "Additionally, the high LINC00958 expression was positively correlated with TNM staging and lymph node metastasis, which is consistent with its role in promoting cancer cell migration and invasion." (PMID 35223488, 2022). "The upregulated expression of LINC00958 was significantly correlated with TNM staging (P < 0.001) and lymph node metastasis (P < 0.001) but not with other factors, including age, smoking history, T stage, M stage, and tumor differentiation." (PMID 35223488, 2022).
oral squamous cell carcinoma (2 papers, 2020 to 2021). "A recent report showed that LINC00958 regulated the miR-627-5p/YBX2 axis and facilitated cell proliferation and migration in oral squamous cell carcinoma." (PMID 32095369, 2020).
bladder tumor (1 paper, 2019). "He and colleagues demonstrated that LINC00958 was upregulated in bladder tumor-associated lymphatic metastasis and lymphangiogenesis." (PMID 31804973, 2019).
disc degeneration (1 paper, 2019). "In summary, we demonstrated that LINC00958 expression was upregulated in degenerative NP samples, and LINC00958 expression increased gradually along with the grade of exacerbation of disc degeneration." (PMID 31804973, 2019). "We found that LINC00958 expression was upregulated in degenerative NP samples, and LINC00958 expression increased gradually along with the grade of exacerbation of disc degeneration." (PMID 31804973, 2019). "Furthermore, we discovered that LINC00958 expression increased gradually along with the grade of exacerbation of disc degeneration." (PMID 31804973, 2019).
esophageal carcinoma (1 paper, 2022). A primary or metastatic malignant neoplasm involving the esophagus. "Our findings demonstrated that LINC00958 is overexpressed in certain specific cancer types, including BLCA, CESC, COAD, esophageal carcinoma (ESCA), HNSC, kidney chromophobe (KICH), kidney renal papillary cell carcinoma (KIRP), LIHC, lung adenocarcinoma (LUAD), LUSC, THCA, and UCEC." (PMID 36437914, 2022).
liver cancer (1 paper, 2022). An epithelial or non-epithelial malignant neoplasm that arises from the liver. "For example, in liver cancer, enhancing LINC00958 stability via METTL3 m6A modification results to its upregulation, which thereby promotes cancer progression." (PMID 36581942, 2022). "In liver cancer, enhancing LINC00958 stability via METTL3 through m6A modification leads to its upregulation, thereby promoting cancer progression." (PMID 36581942, 2022).
ovarian carcinoma (1 paper, 2026). A malignant neoplasm originating from the surface ovarian epithelium. "In contrast, the immunoregulatory functions of CYP4A22-AS1 and LINC00958 remain less explored, with only one recent study indicating that exosomal LINC00958 induces M2 macrophage polarization to maintain stemness in ovarian cancer." (PMID 41614894, 2026).
prostate adenocarcinoma (1 paper, 2022). "In contrast, LINC00958 expression was low in BRCA and prostate adenocarcinoma (PRAD)." (PMID 36437914, 2022).
tumor (24 papers, 2019 to 2026). "In vivo, tumor growth was inhibited by loss of linc00958 in mice." (PMID 36056431, 2022). "In this research, we further discovered that in vitro, depletion of RSF-1 in SiHa/DDP cells could attenuate the cisplatin resistance and tube formation; in xenograft mice, RSF-1 was decreased by the knockdown of linc00958 and associated with the inhibition of tumor growth and angiogenesis." (PMID 36056431, 2022). "RT‐qPCR showed elevated LINC00958 expression and reduced miR‐129‐2‐3p levels in tumor tissues from the Lv‐oe‐LINC00958 group (p < 0.01)." (PMID 41090505, 2025). "In vivo xenograft experiments using Ishikawa cells supported the in vitro findings, confirming that LINC00958 promotes tumor growth by modulating the miR‐129‐2‐3p/NOTCH3 axis." (PMID 41090505, 2025). "Up-regulated LINC00958 promotes tumor cell proliferation and promotes tumor growth in mice through the LINC00958/miR-378a-3p/YY1 axis." (PMID 37901333, 2023). "In a patient-derived xenograft (PDX) mouse model of HCC, the authors observed that LINC00958 overexpression promotes tumor growth, while its silencing downregulates tumor growth." (PMID 37111734, 2023). "LINC00958 knockdown decreased tumor volume and size, as well as the tumor weight, in the A549 cell xenograft mouse model." (PMID 35223488, 2022). "In the present research, LINC00958 was markedly overexpressed in BC tissue and cells, and LINC00958 upregulation promoted the tumor progression of BC cells." (PMID 33531456, 2021). "Several studies have suggested that LINC00958 and HOXC13-AS are significantly associated with tumor progression, migration, and invasion." (PMID 32095369, 2020). "Through qRT-PCR analysis, we observed that LINC00958 expression was higher in LAD tissues in contrast to adjacent non-tumor tissues." (PMID 31997940, 2020). "We found that LINC00958 knockdown resulted in a blunted tumor growth in terms of tumor weight and volume, whereas LINC00958 overexpression accelerated tumor growth." (PMID 31915027, 2020). "To confirm that LINC00958 exerted the tumor-promoting effects via miR-3619-5p, we upregulated the expression of miR-3619-5p in LINC00958-overexpressed Hep3B cells and conducted rescue experiments." (PMID 31915027, 2020). "Additionally, LUAD cell lines and orthotopic tumor xenografts have been employed to study ATF4 activation of LINC00958, validating its contribution to immune escape and tumor progression." (PMID 40777108, 2025). "The expression of LINC00958 was upregulated in clinical tumor samples." (PMID 35223488, 2022). "IHC showed that RSF-1 and the tumor growth biomarker Ki67, were inhibited in the group where linc00958 was knocked down, revealing that linc00958 downregulation in mice could inhibit RSF-1 and Ki67, suppressing the tumor growth." (PMID 36056431, 2022). "IHC results also validated that linc00958 downregulation could inhibit the tumor microvessel density marker CD34 and VEGFA in tumors, supporting that the knockdown of linc00958 inhibited the angiogenesis in xenograft model." (PMID 36056431, 2022). "We found that LINC00958 knockdown could inhibit tumor growth and diminish tumor volume and weight, but then these effect was reversed by overexpressing CPSF7." (PMID 31997940, 2020). "LINC00958 might act as an oncogenic factor affecting tumor progression." (PMID 36437914, 2022). "Thus, LINC00958 may also be involved in the communication between cancer cells and tumor immune microenvironment." (PMID 35223488, 2022). "In HCC, METTL3 promotes tumor growth by regulating oncogenic and tumor-suppressing genes, including SNAIL, YAP1, LINC00958, and SOCS2." (PMID 40302799, 2025). "The knockdown of linc00958 inhibited RSF-1 and Ki67, curbing tumor growth; it also inhibited VEGFA and CD34, decreasing angiogenesis in mice." (PMID 36056431, 2022). "The results showed that MYOSLID, LINC00958, and AL022328.2 were expressed more, while AL450992.2 and AC068580.1 were expressed less, in tumor compared to normal tissues." (PMID 34660307, 2021).
tumor (continued). "In contrast, co‐transfection with Lv‐oe‐LINC00958 and miR‐129‐2‐3p agomir led to increased miR‐129‐2‐3p expression, decreased NOTCH3 levels (p < 0.05), and a reversal of LINC00958‐induced tumor growth (p < 0.05)." (PMID 41090505, 2025). "Taken together, this study reported a new regulatory axis linc00958/miR-185-5p/RSF-1 in cisplatin resistance and tube formation in CC via AKT1/GSK3β/VEGFA pathway and knockdown of linc00958 could also inhibit the tumor growth and angiogenesis." (PMID 36056431, 2022). "In CC mice with knockdown of linc00958, the tumor microvessel density biomarker CD34 and VEGFA were significantly inhibited, revealing that knockdown of linc00958 could attenuate tumor angiogenesis." (PMID 36056431, 2022). "Overexpression of NUDT19 and the mTORC1 activator MYH1485 reverse the inhibitory effects of LINC00958 silencing on HCC proliferation, migration, and epithelial‐mesenchymal transition (EMT), and a large number of newly identified lncRNAs that are specifically expressed in tumor groups were found." (PMID 39630113, 2025). "Hence, in this study, we investigated the regulatory effect of linc00958/miR-185-5p/RSF-1 on cisplatin resistance in SiHa/DDP cells and tube formation in vitro; in xenograft mice, we further validated the role of linc00958 in tumor growth and angiogenesis." (PMID 36056431, 2022). "Furthermore, we found that LINC00958 was highly up-regulated in tumor tissues, compared with normal tissues from the TCGA database." (PMID 33658048, 2021).